ESRRB (estrogen related receptor beta)
Diseases named in the same sentence as ESRRB in open-access papers:
ESRRB is named in the same sentence as 110 diseases in open-access papers, as found by Europe PMC text mining. Sharing a sentence is not in itself a finding about the gene and the disease. The quoted sentences say what the papers report.
breast carcinoma (65 papers, 2007 to 2025). "In an entirely different context linked to breast cancer, estrogen-related receptor beta (ERRβ) has been identified as a substrate for the E3 ligase SCF complex, leading to cullin-dependent degradation." (PMID 39623094, 2024). "KDM5B, ARSB, AKR1C3, HSD3B1, ESRRB are involved in steroid hormone metabolism and have been found to be associated with other hormone-dependent tumors, such as prostate and breast cancers." (PMID 36742386, 2023). "The overexpression of estrogen-related receptor beta (ERRβ) is positively associated with the improved prognosis and prolonged survival in breast cancer patients." (PMID 37771770, 2023). "Our observations in a breast cancer cell line support the multifaceted roles of ESRRB, where ESRRB demonstrated a similar pattern of binding and activity." (PMID 41516107, 2025). "Estrogen-related receptor beta (ERRβ) is downregulated in breast cancer cells and its overexpression in breast cancer patients is positively correlated with an improved prognosis and prolonged relapse-free survival." (PMID 32839427, 2020). "Conversely, ESRRB has been shown to inhibit breast cancer proliferation." (PMID 40356747, 2025). "Although further investigation is needed to elucidate the role of ESRRB in TNBC, ESRRB may be a promising therapeutic target in breast cancer." (PMID 41516107, 2025). "Besides this, estrogen-related receptor beta (ERRβ) has also been proposed to have multiple anti-proliferative properties in breast cancer cells." (PMID 32839427, 2020). "And ESRRB (or ERRβ) is a negative regulator of cell cycle and may be a therapeutic target for breast cancer." (PMID 33042807, 2020).
prostate carcinoma (19 papers, 2011 to 2025). A carcinoma that arises from epithelial cells of the prostate gland. "The enrichment of the FoxO pathway in up-regulated DEGs is also consistent with the role of ESRRB as a tumor suppressor in breast and prostate cancers, as well as the association of ESRRB overexpression with improved prognosis." (PMID 41516107, 2025).
hearing loss (11 papers, 2011 to 2024). "Homozygous missense variants in RDX (OMIM 179410), CABP2 (OMIM 607314), and ESRRB (OMIM 602167) were found to contribute to hearing loss in three individuals." (PMID 32681043, 2020). "ESRRB is an estrogen related receptor beta gene which is known to cause hearing loss at DFNB35 (OMIM 608565) locus." (PMID 32681043, 2020). "Congenital forms of hearing impairment can be caused by mutations in the estrogen related receptor beta (ESRRB) gene." (PMID 25023176, 2014). "ESRRB, a gene when mutated causes a form of hearing impairment, also contributes to dental decay likely by influencing the formation of an enamel surface more susceptible to demineralization under acidic conditions." (PMID 25023176, 2014). "The DFNB35 family from the Czech Republic has a recessive missense mutation (R291L) in ESRRB and hearing impairment." (PMID 25023176, 2014). "Two families with DFNB35 hearing loss and ESRRB mutations were contacted for this study, one from Turkey and the other from the Czech Republic." (PMID 25023176, 2014). "The identification of the deletion mutation of ESRRB gene will expand our understanding of hearing impairment due to mutations in the estrogen-related gene ESRRB." (PMID 22567352, 2011). "ESRRB mutations are identified to result in congenital hearing impairment in human." (PMID 38413848, 2024). "Loss-of-function mutations of ESRRB are causatively linked to hereditary hearing loss in humans." (PMID 36034227, 2022). "The rationale for this suggestion comes from the hypothesis that ESRRB could cause congenital forms of hearing impairment as well as increased susceptibility to the acquired forms of hearing loss." (PMID 25023176, 2014). "Here we investigated whether loss of function of ESRRB, which in humans leads to hearing impairment, also leads to increased dental caries experience." (PMID 25023176, 2014). "The common etiology of dental caries and hearing impairment provides a venue to assist in the identification of individuals at risk to either condition and provides options for the development of new caries prevention strategies, if the associated ESRRB genetic variants are correlated with efficacy." (PMID 25023176, 2014). "Among the genes identified via FST and XP-EHH analyses, four are actually associated with hearing loss: CADM1, ESRRB, AKT3, and ATP2B2." (PMID 37570247, 2023). "Of the 17 Turkish DFNB35 family members with a recessive seven base pair duplication in exon 8 of ESRRB (c.1018_1024dupGAGTTTG) and hearing impairment contacted by phone interview, 15 provided information regarding their dental caries experience." (PMID 25023176, 2014). "For example, mutations of several genes involved in oestrogen signalling lead to hearing impairment, such as Esr2, Esrrb and Esrrg in mice and ESRRB in human deafness type DFNB35, and hearing impairment is a feature of oestrogen deficiency in Turner syndrome in humans." (PMID 26881968, 2016).
ovarian carcinoma (6 papers, 2008 to 2023). A malignant neoplasm originating from the surface ovarian epithelium. "No data exists regarding ESRRB expression in porcine granulosa cells in relation to cell proliferation in vitro; however, there are several findings indicating the role of estrogen-related receptors in ovarian cancer growth, progression, and metastasis." (PMID 28116305, 2016). "In contrast to the chemerin protein data from IHC, mRNA levels of the RARRES2 gene in ovarian cancer were not correlated with PGR, ESR2, ESRRA, ESRRB, ESRRG, nor CEACAM5 after analysis of both patient collectives on the mentioned platforms (p > 0.05 for all)." (PMID 36900088, 2023).
breast tumors (5 papers, 2016 to 2024). "High levels of total ESRRB mRNA in primary breast tumors are associated with a reduction in cells in S phase and increased expression of estrogen receptor beta (ERβ)." (PMID 27363015, 2016). "In addition, ESRRA was downregulated in breast tumors but upregulated in the other tumors, and ESRRB and ESRRG were upregulated in breast, ovarian, and endometrial tumors." (PMID 38582811, 2024).
Obesity (5 papers, 2013 to 2022). Accumulation of substantial excess body fat. "Orphan nuclear receptors, such as estrogen related receptor alpha and estrogen related receptor beta, have been found to play a role in metabolic disease, weight gain, and obesity when exposed to EDCs such as Bisphenol AF." (PMID 34899613, 2021).
cervical cancer (3 papers, 2025). A primary or metastatic malignant neoplasm involving the cervix. "Nonetheless, this study revealed that ESRRB was overexpressed in cervical cancer and linked with disease progression, whereas ESRRB knockout in cervical cancer cells triggered cell-cycle arrest, causing interference of cell proliferation in vitro and diminished tumor growth in vivo." (PMID 40565012, 2025). "Interestingly, ESRRB has been shown to promote cell proliferation by suppressing the TGF-beta signaling pathway in cervical cancer." (PMID 41516107, 2025).
rotator cuff tears (3 papers, 2018 to 2022). "They identified high-risk haplotypes in the ESRRB gene comparing genotypes of 175 patients with rotator cuff tears with 2595 genetically-matched Caucasian controls." (PMID 31477042, 2019).
acute lymphoblastic leukemia (2 papers, 2018 to 2024). Leukemia with an acute onset, characterized by the presence of lymphoblasts in the bone marrow and the peripheral blood. "Previous studies have shown that ESRRB repression in acute lymphoblastic leukemias, which are closely related to B-cell lymphomas, contributes to treatment resistance." (PMID 39336806, 2024).
autosomal dominant non-syndromic hearing loss (2 papers, 2022 to 2023). "The next most significant gene in our data was ESRRB (FDR = 0.06, p = 7.0×10−4), a nuclear receptor associated with autosomal recessive hearing loss." (PMID 36656851, 2023). "The ESRRB gene is the only known gene that acts as a transcription factor and is associated with ARNSHL, while other transcription factors are related to autosomal dominant non-syndromic hearing loss (ADNSHL)." (PMID 35101039, 2022).
deafness (2 papers, 2014 to 2019). An inherited or acquired condition characterized by the complete loss of the ability to hear from one or both ears. "All seven of these families have variants in seven different known deafness genes, LRTOMT, LHFPL5, TMPRSS3, OTOF, MYO15A, ESRRB, and KCNE1." (PMID 31835641, 2019).
psychosis (2 papers, 2008 to 2022). "In a recent GWAS meta-analysis, a SNP at the ESRRB loci was among the top 25 genetic variants most strongly associated with cognitive performance in subjects with psychotic disorders." (PMID 36109771, 2022).
schizophrenia (2 papers, 2011 to 2015). A major psychotic disorder characterized by abnormalities in the perception or expression of reality. "As outlined in S11 Table, seven of these genes have, to varying degrees, plausible links to cognition (i.e. DGKB, NPS, VPS13B, RBM20, ABHD4, ESRRB, and DOPEY2), with some active in systems implicated in schizophrenia pathology (NPS, DGKB, ABHD4, ESRRB)." (PMID 25860228, 2015).
dental caries (1 paper, 2014). The decay of a tooth, in which it becomes softened, discolored, and/or porous. "We tested for association between the ESRRB locus and dental caries in 1,731 subjects, if ESRRB was expressed in whole saliva, if ESRRB was associated with the microhardness of the dental enamel, and if ESRRB was expressed during enamel development of mice." (PMID 25023176, 2014). "We showed that SNPs in the ESRRB locus are also associated with dental caries experience in multiple populations, but particular populations are less influenced by factors that protect against the disease." (PMID 25023176, 2014). "Through experiments that tested the effects of acid dissolution of the enamel surface, we reasoned that ESRRB variants contributes to formation of an enamel structure that is more susceptible to the acidic effects involved in the initiation of dental caries." (PMID 25023176, 2014). "ESRRB is located in the 14q24.3 locus, which was linked to dental caries through a genome-wide linkage scan." (PMID 25023176, 2014). "In a dominant model, statistical association was found between ESRRB expression and rs10132091 genotypes (p = 0.03), between low dental caries experience and rs10132091 genotypes (p = 0.05), and between low ESRRB expression in whole saliva of adults and rs6574293 genotypes (p = 0.04)." (PMID 25023176, 2014). "We also found statistical evidence of an interaction between ESRRB SNPs and a SNP predicted to disrupt a GR binding site in families with high dental caries experience." (PMID 25023176, 2014). "We found statistical evidence that rs17074565 and ESRRB SNPs are over-transmitted together in families with high dental caries experience." (PMID 25023176, 2014). "Expression levels of ESRRB in whole saliva samples showed differences depending on sex and dental caries experience." (PMID 25023176, 2014). "The ten members of the family who are carriers for the ESRRB mutation (six homozygous, four heterozygous) have severe dental caries, with many if not all teeth affected by caries." (PMID 25023176, 2014).
epidermoid carcinoma (1 paper, 2014). "Additionally, expression of the short ESRRB isoform was detected in the submaxillary salivary gland epidermoid carcinoma cell line HTB-41TM." (PMID 25023176, 2014).
RASopathy (1 paper, 2017). Developmental syndromes caused by germline mutations (or in rare cases by somatic mosaicism) in genes that alter the Ras subfamily and mitogen-activated protein kinases that control signal transduction. "Additional genes listed in SFARIgene adjacent to our top RASopathy social responsiveness QTL results include CNTN5, ESRRB, GABRB1, GNB1L, and ICA1." (PMID 28076348, 2017).
tendon disease (1 paper, 2018). "There is evidence of an association between SNPs in the estrogen-related receptor beta (ERRβ) and tendon disease." (PMID 30537990, 2018).
teratoma (1 paper, 2019). A non-seminomatous germ cell tumor characterized by the presence of various tissues which correspond to the different germinal layers (endoderm, mesoderm, and ectoderm). "Ablation of ESRRB O-GlcNAc impairs its function for maintaining mESC self-renewal and pluripotency, both in cell culture and during teratoma formation in mice." (PMID 31492838, 2019).
cancer (65 papers, 2007 to 2026). A tumor composed of atypical neoplastic, often pleomorphic cells that invade other tissues. "Several mechanisms have been proposed for ESRRB’s tumor-suppressive effects, including the induction of cancer cell apoptosis, arrest of cell proliferation in the G1 phase, and inhibition of epithelial–mesenchymal transition (EMT)." (PMID 41516107, 2025). "Our findings reveal that ESRRA predominantly acts as an oncogene in multiple cancer types, whereas ESRRB and ESRRG exhibit distinct roles across different tumors." (PMID 40356747, 2025). "Although ESRRB is a multifaceted transcription factor with diverse roles in several cellular processes, its role in cancer remains ambiguous with research predominantly conducted in rodent embryonic and reprogrammed cells due to its function as a stemness/pluripotency factor." (PMID 41516107, 2025). "ESRRB, though less studied, has shown tumor-suppressive properties in some cancers." (PMID 40356747, 2025). "The top scoring TF motifs in cancer cells that associated with sensitive H3K4me3 peak width dynamics tended to involve cancer-associated TFs such as c-MYC and ETS in cancer cells and liver-specific TFs such as RXR and ESRRB in liver." (PMID 29769529, 2018). "First, we compared the fold change in expression of the ER-related receptors ESR1, ESR2, ESRRA, ESRRB, ESRRG, and GPER1 in the four female cancers." (PMID 38582811, 2024). "SETD5 overexpression causes the upregulation of PI3K-AKT pathway-related genes and cancer stem cell (CSC) markers such as CD133, Kruppel-like factor 4 (KLF4), and estrogen-related receptor beta (ESRRB), leading to the gain of stem cell-like phenotypes." (PMID 37963940, 2023). "In predominant cancer types, QUANTISEQ revealed the close correlation of ESRRB with the infiltration level of B cells and macrophages M2, while CIBERSOR showed a substantial contribution of ESRRB to Treg infiltration in CHOL." (PMID 40356747, 2025). "Predominant cancer types exhibited a positive correlation between ESRRA and stemness scores, while a negative correlation between stemness scores and ESRRB as well as ESRRG was established." (PMID 40356747, 2025).
tumor (63 papers, 2012 to 2025). "Moreover, further investigations using normal human cells, particularly adult stem cells, are essential to elucidate the role of ESRRB in tumor initiation." (PMID 41516107, 2025). "Estrogen related receptor beta is present in 45–70% pf NSCLC tumors in both sexes, making hormonal influences on tumor biology an appealing hypothesis." (PMID 31247015, 2019).
ESRRB also shares sentences with these, for which no sentence is quoted: pancreatic cancer (6 papers); glioblastoma (5); Hearing impairment (5); hepatocellular carcinoma (5); melanoma (5); Parkinson disease (4); bladder cancer (3); colorectal cancer (3); diabetes (3); gastric cancer (3); head and neck squamous cell carcinoma (3); liver fibrosis (3); lung carcinoma (3); adenocarcinoma (2); adrenal hypoplasia congenita (2); Arthritis (2); atherosclerosis (2); cardiovascular disease (2); head and neck cancer (2); Infertility (2); metabolic disease (2); non-small cell lung carcinoma (2); Sepsis (2); triple-negative breast carcinoma (2); adrenal hypoplasia (1); adrenocortical adenomas (1); adrenocortical carcinomas (1); Anxiety (1); asthma (1); autism spectrum disorder (1).
A further 60 diseases each share a sentence with ESRRB in 1 paper.